EGFR (epidermal growth factor receptor)
Diseases named in the same sentence as EGFR in open-access papers (continued):
Sharing a sentence is not in itself a finding about the gene and the disease.
chronic lung disease (3 papers, 2018 to 2022). According to the definitions of the American and British Thoracic Societies, including pulmonary functional tests, X-rays, and CT scans for items such as fibrosis, bronchiectasis, bullae, emphysema, nodular or lymphomatous abnormalities. "Here, we review evidence suggesting that hyperactivity of the EGFR/ADAM17 axis plays a role in the development of chronic lung disease in both CF and COPD." (PMID 29540993, 2018). "Further studies revealed that this rare nonsynonymous variant (p.N370K, in the fourth FNIII domain of GLEPP1) attenuated EGFR signaling in response to several stimuli in primary epithelial cells, which fits with earlier reports on a link between the EGFR pathway and chronic lung diseases." (PMID 36755664, 2022). "So far, polymorphisms associated with the ADAM17, AREG, or EGFR genes have not been directly linked to chronic lung disease, but that may be due to limitations of the studies." (PMID 29540993, 2018). "In this review, we focus on a signaling pathway called the EGFR/ADAM17 axis and its potential role in chronic lung disease, in particular CF and COPD." (PMID 29540993, 2018).
congenital heart disease (3 papers, 2022 to 2023). A heart disease that is present at birth. "Our data provide evidence for the integrity of the EGFR signaling pathway in the pathophysiology of neointimal formation in SP shunts from children with complex congenital heart disease." (PMID 36867212, 2023). "Since the pathophysiology of neointimal hyperplasia in SP shunts of infants with complex congenital heart disease remains largely unknown, we aimed to identify the role of EGFR and MMP-9 in the formation of neointima in SP shunts." (PMID 36867212, 2023). "Novel approaches, such as coating PTFE shunts with agents specifically suppressing pathways around EGF/EGFR and TIMP-1/MMP-9, might significantly reduce neointimal hyperplasia in SP shunts and therefore improve the outcome of children with complex and congenital heart defects." (PMID 36867212, 2023).
conjunctival squamous cell carcinoma (3 papers, 2010 to 2020). A low-grade squamous cell carcinoma that arises from the conjunctiva. "Factors associated with conjunctival cancer, determining if conjunctival squamous cell carcinoma (CSCC) harbors human HPV DNA and if CSCC is associated with activation of epidermal growth factor receptor (EGFR) signaling pathway were investigated." (PMID 32704483, 2020). "EGFR is important in the pathology of ocular surface squamous neoplasia including SCC and is a prognostic factor." (PMID 32833992, 2020). "In other words, activation of the EGFR pathway in conjunctival squamous cell carcinoma appears to play a role in genetic alteration to maintain a malignant phenotype, as a consequence of the genomic instability associated with HPV infection." (PMID 20498858, 2010).
conjunctivitis (3 papers, 2022 to 2025). Inflammation of the conjunctiva of the eye. "Epidermal growth factor receptor inhibitors, used in the treatment of several cancers, have been associated with conjunctivitis, meibomitis, dry eye, periocular skin changes, and trichomegaly." (PMID 41025570, 2025). "However, a significant correlation was found with the use of EGFR inhibitors, indicating a higher likelihood of experiencing conjunctivitis and scleritis in 18.41% of patients (37/201) (p = 0.008, odds ratio = 5.65, 95% CI = 1.76-18.19)." (PMID 37347077, 2023).
corneal ulcer (3 papers, 2012 to 2022). Area of epithelial tissue loss from corneal surface; associated with inflammatory cells in the cornea and anterior chamber. "It is known that EGFR is intimately involved in angiogenesis and wound healing; as such, it is not surprising that the most severe ocular toxicities associated with this class of agent included complications with delayed wound healing, such as corneal ulceration." (PMID 28938590, 2017). "However, sight-threatening ocular adverse effects, like corneal ulcer and perforation, can occur due to the expression of EGFR on limbal and conjunctival epithelia." (PMID 36320985, 2022).
craniopharyngioma (3 papers, 2019 to 2025). A benign, partly cystic, epithelial tumor of the sellar region, presumably derived from Rathke pouch epithelium. "This study verified the influence of EGFR signaling on the migration of craniopharyngioma cells in vitro, indicating that EGFR inhibitors may be a promising therapeutic option for ACP." (PMID 40113789, 2025). "Despite these advancements in the management of papillary craniopharyngiomas, limited progress has been made in the management of adamantinomatous craniopharyngiomas, where a range of different molecular therapies have been employed (anti-EGFR, anti-IL6 and anti-VEGF) with heterogenous results." (PMID 39456573, 2024). "Furthermore, EGFR expression has been reported in craniopoharyngioma and EGFR phosphorylation has been shown to enhance adamantinomatous craniopharyngioma cell migration and has been proposed as an escape mechanism for radiation therapy." (PMID 31712784, 2019).
Crohn disease (3 papers, 2016 to 2023). A gastrointestinal disorder characterized by chronic inflammation involving all layers of the intestinal wall, noncaseating granulomas affecting the intestinal wall and regional lymph nodes, and transmural fibrosis. "It has been shown that EpCAM+EGFR+ cells were found in benign inflammatory colon diseases, such as Crohn disease." (PMID 36613466, 2022).
cryptogenic organizing pneumonia (3 papers, 2013 to 2025). Cryptogenic organizing pneumonia (COP) is a form of idiopathic interstitial pneumonia characterized pathologically by organizing pneumonia (OP) that presents with non-specific flu-like symptoms, as well as cough and dyspnea and where no etiological agent is found. "In the study of Tzouvelikis and co-authors, lung tissue samples of IPF, cryptogenic organizing pneumonia (COP), and NSIP patients were analyzed for epidermal growth factor receptor (EGFR)." (PMID 25733981, 2015).
Cushing syndrome (3 papers, 2022 to 2025). Cushing's syndrome (CS) encompasses a group of hormonal disorders caused by prolonged and high exposure levels to glucocorticoids that can be of either endogenous (adrenal cortex production) or exogenous (iatrogenic) origin. "LC-TPIT primarily includes genes implicated in Cushing syndrome (e.g., POMC, EGFR), and LC-SF1 is enriched for components of the GnRH signaling pathway (e.g., LHB, FSHB)." (PMID 41253784, 2025).
dengue (3 papers, 2015 to 2021). "Therefore, vandetanib inhibition of VEGFR-induced vasodilation or EGFR-mediated alterations in cell physiology may alleviate hemorrhagic symptoms caused by severe dengue." (PMID 33173007, 2020). "Clinical studies have correlated severe dengue disease with reduced abundance of prostasin, which reduces EGFR expression; further, EGFR knockout reduced dengue pathogenesis in a suckling mouse model." (PMID 33173007, 2020). "We found that the same m336-specific VH/VL pairing, IGHV1-69/IGK1-17, exists in the dengue cross-reactive hybridoma-derived mAb 2H12 and anti-Homo sapiens epidermal growth factor receptor (EGFR) antibody, imgatuzumab, indicating the immunologically relevant cognate VH/VL pairing type for m336." (PMID 26370782, 2015).
diffuse intrinsic pontine glioma (3 papers, 2016 to 2021). A neuroglial tumor that arises from the middle portion of the brain stem. "This study investigates the safety, tolerability, and preliminary efficacy of combined treatment with VEGF inhibitor bevacizumab, topoisomerase I inhibitor irinotecan, and EGFR inhibitor erlotinib in children with progressive diffuse intrinsic pontine glioma (DIPG)." (PMID 33963476, 2021). "Based on a pediatric sub-study nested with INTELLANCE 2, the FDA granted rare pediatric disease designation to the drug for the treatment of children with EGFR-amplified diffuse intrinsic pontine glioma (DIPG)." (PMID 31159480, 2019).
fibroma (3 papers, 2022 to 2023). A non-metastasizing neoplasm arising from the fibrous tissue. "Additionally, RHAMM may co-activate ERK1/2 by partnering with upstream activators such as PDGFR and epidermal growth factor receptor (EGFR) in mesenchymal and fibroma cells respectively to promote cell motility." (PMID 36033439, 2022).
focal segmental glomerulosclerosis (3 papers, 2018 to 2024). A renal disorder characterized by sclerotic lesions in the glomeruli. "The activation of EGFR has been connected to the progression of several nephropathies like diabetic and membranous nephropathy, focal segmental glomerulosclerosis (FSGS) and rapidly progressive glomerulonephritis." (PMID 29549365, 2018). "To define the role of EGFR-mediated FUS nuclear translocation in glomerular injury, we induced glomerular injury in mice via administration of adriamycin (ADR), a well-established model of focal segmental glomerulosclerosis." (PMID 38488009, 2024).
gastric disease (3 papers, 2022 to 2025). "Ample evidence has revealed a strong association between EGFR and gastric diseases." (PMID 35066729, 2023). "TGFA/EGFR signaling is not only important for maintaining pit homeostasis but also appears to be responsible for the progression of human gastric disease." (PMID 41365858, 2025). "In addition, the phosphorylated EGFR level in the gastric tissues of patients with gastric disease developing to intestinal metaplasia or dysplasia were higher than those of patients without disease progression." (PMID 35066729, 2023). "Furthermore, long-term exposure to TGFA/EGFR signaling in Rab25 KO mice can induce gastric disease." (PMID 41365858, 2025).
Gliosis (3 papers, 2016 to 2023). Gliosis is the focal proliferation of glial cells in the central nervous system. "The sensitivity and specificity of the negative staining for the diagnosis of gliosis were as follows: EGFR—100% sensitive, 32.8% specific; MEOX2—97.7% sensitive, 37.5% specific; SOX11—79.5% sensitive, 46.6% specific and INSM1—97.7% sensitive, 47.8% specific." (PMID 37568909, 2023).
granulosa cell tumor (3 papers, 2010 to 2025). A slow-growing, malignant tumor, characterize by the presence of granulosa-like cells and Call-Exner bodies, that is almost always found in the ovary. "Our previous study also showed that FHL2 expression level was correlated with EGFR expression in the human granulosa cell tumor cell lines KGN and COV434." (PMID 37015904, 2023). "Our findings herein suggest that the inhibition of EGFR, either as a stand-alone therapy or in combination with other approaches, might be a good approach for the treatment of granulosa cell proliferation dysfunction, granulosa cell tumors or other cancers that exhibit elevated HOX gene expression." (PMID 20540809, 2010).
hemangioblastoma (3 papers, 2016 to 2025). "Our findings are in line with three prior immunohistochemical studies that found EGFR overexpression in hemangioblastomas." (PMID 26768750, 2016). "EGFR is the only gene that has been previously reported as a candidate gene with hemangioblastoma." (PMID 26768750, 2016). "In this study, we have demonstrated in two different tumor cohorts and using two different techniques for copy number alteration detection, SNP and digital PCR, that Chek2 is deleted and EGFR, PTPN11, Ptch1 amplified in majority of hemangioblastoma patients." (PMID 26768750, 2016). "Overexpression EGFR and TGFα may contribute to tumor growth in VHL-related hemangioblastomas." (PMID 32432044, 2020). "However, at present, the role of EGFR and TGFα in VHL-associated hemangioblastomas has not been examined." (PMID 32432044, 2020). "Hemangioblastomas are usually positive for alpha-inhibin, D2-40, brachyury, NSE, NCAM1, S100, ezrin, CXCR4, aquaporin-1, and occasionally for GFAP and EGFR, and negative for EMA, CD10 and CAM5.2." (PMID 41302074, 2025).
hereditary cancer syndromes (3 papers, 2017 to 2024).
insomnia (3 papers, 2022 to 2025). A sleep disorder characterized by difficulty in falling asleep and/or remaining asleep. "EGFR is directly and multi-dimensionally linked to insomnia through regulation of the SCN circadian rhythm and the MAPK/ERK–NPVF sleep pathway." (PMID 41367024, 2025). "It is worth noting that, although this study focused on EGFR, insomnia involves multiple signaling pathways, such as GABAergic metabolism, serotonergic signaling, and melatonin secretion regulation." (PMID 41367024, 2025). "By introducing core clusters for pathway analysis, it was found that the four Chinese medicinals played a therapeutic role in the ErbB signal pathway, cancer pathway, EGFR tyrosine kinase inhibitor resistance, and insulin signal pathway to treat insomnia." (PMID 35769674, 2022).
kidney stone (3 papers, 2021 to 2025). "The results suggest that a total of eight test indicators are closely associated with the incidence of kidney stones (FDR p value < 0.05), including eight blood test indicators (CRE, EGFR, CA, UAHDL, APOA, CYS and URNA)." (PMID 40673688, 2025). "CRE, CYS and UA help prevent kidney stones, whereas higher concentrations of EGFR, CA, HDL, APOA and URNA contribute to their formation." (PMID 40673688, 2025). "OATF effectively inhibited kidney stone formation and mitigated renal injury by attenuating oxidative stress and apoptosis through activation of the EGFR/PI3K/AKT pathway." (PMID 40432899, 2025). "Direct causal relationships were established between kidney stones and 9 dietary factors (including fruit, alcohol, coffee intake), 11 gut microbiota types, 8 metabolites, 12 plasma proteins and 8 laboratory indicators (CRE, EGFR, CA, UAHDL, APOA, CYS and URNA)." (PMID 40673688, 2025). "Notably, experimental results confirmed that OATF reduces CaOx crystal deposition by modulating the EGFR/PI3K/AKT signaling pathway, highlighting its protective role in kidney stone formation." (PMID 40432899, 2025). "Our study confirms the anti-apoptotic effects of OATF in ex vivo models and identifies the EGFR/PI3K/AKT signaling pathway as a key mechanism, as predicted by network pharmacology, that may influence kidney stone formation." (PMID 40432899, 2025).
lentivirus infection (3 papers, 2018 to 2025). Virus diseases caused by the Lentivirus genus. "The gene-edit efficiency by TIDE analysis on EGFR sgRNA_2 lentivirus infection shows to have considerable efficiency with 72.4% of the cell pool that was edited." (PMID 29849821, 2018). "In addition, lentivirus infection of both EGFR sgRNA_1 and EGFR sgRNA_2 was shown by TIDE analysis to have considerable gene-editing efficiency: 88.2% and 86.1% of the cell pool was edited, respectively." (PMID 29849821, 2018). "To eliminate the interference from lentivirus infection process, we also compared normal oral mucosal epithelial cells (HIOECs) with CAL27 cells, which owns the naturally occurring EGFR overexpression during the malignant transformation of OSCC." (PMID 39816681, 2025). "The EGFR-mutant human LUAD cell line HCC4006 was implanted with sh-RNA for ARID1A and the NC vector after lentivirus infection." (PMID 36229854, 2022).
Leukoencephalopathy (3 papers, 2014 to 2022). This term describes abnormality of the white matter of the cerebrum resulting from damage to the myelin sheaths of nerve cells. "In univariate analysis, female, age ≥ 60 year-old, and history of EGFR-TKI treatment were risk factors for grade 2 leukoencephalopathy, and only history of EGFR-TKI treatment remained statistically significant in multivariate analysis." (PMID 24884773, 2014). "In patients with leukoencephalopathy, 4 patients had EGFR 19del and 2 patients had L858R." (PMID 34865626, 2021).
lipoma (3 papers, 2015 to 2025). A benign, usually painless, well-circumscribed lipomatous tumor composed of adipose tissue. "Both VEGF and epidermal growth factor receptor (EGFR) have been implicated in lipoma development." (PMID 40225498, 2025). "Most studies have investigated the association between EGFR and VEGF in malignant tumors,12)-(14 while little is known about the role of these proteins in benign mesenchymal tumors such as lipomas." (PMID 37194849, 2023). "In the present study, EGFR immunostaining was higher in lipomas than in normal adipose tissue (37.5%) and this difference was statistically significant." (PMID 37194849, 2023). "Ademais, nos lipomas clássicos foi percebido que os adipócitos imunomarcados para EGFR estiveram diretamente proporcionais a imunoexpressão de VEGF, apresentando correlação do tipo moderada, positiva e estatisticamente significativa (r=0,566; p = 0,005)." (PMID 37194849, 2023). "In classic lipomas, the number of EGFR-immunostained adipocytes was directly proportional to the number of VEGF-positive cells, demonstrating a significant moderate positive correlation (r=0.566, p=0.005)." (PMID 37194849, 2023). "A statistically significant difference in EGFR immunoexpression (p=0.047), especially, between classic lipomas and normal adipose tissue." (PMID 37194849, 2023). "EGFR was overexpressed in lipomas, especially in classic lipomas with a median score of 65.0, followed by non-classic lipomas (median = 42.4) and normal adipose tissue (median = 33.8)." (PMID 37194849, 2023). "The present study used 54 oral lipoma specimens to investigate the immunoexpression of EGFR and VEGF proteins involved in tumor proliferation, growth, and angiogenesis." (PMID 37194849, 2023). "Additionally, some lipoma cases exhibited EGFR positivity, highlighting a possible but yet undefined involvement of EGFR signaling in lipoma formation." (PMID 40225498, 2025). "In classic lipomas, the number of EGFR-immunostained adipocytes was directly proportional to the number of VEGF-positive cells, demonstrating a significant moderate positive correlation (r=0.566, p=0.005), although MVC was not significantly correlated with EGFR immunoexpression in this tumor." (PMID 37194849, 2023). "In addition, there was a statistically significant difference in EGFR expression (p=0.047), especially, between classic lipomas and normal adipose tissue by Dunn’s post hoc test (p=0.041)." (PMID 37194849, 2023). "Dessa forma, essa pesquisa teve como objetivo detectar, quantificar e comparar a expressão imunoistoquímica do EGFR, VEGF e contagem microvascular (MVC) dos lipomas orais, relacionando-os com as características clínicas e morfológicas dos casos estudados." (PMID 37194849, 2023). "EGFR immunopositivity was detected in 56.6% of cells in classic and non-classic lipomas, while this percentage was 37.5% in normal adipose tissue." (PMID 37194849, 2023). "Com base nos resultados, pode-se sugerir que o EGFR, VEGFR e MCV participam do desenvolvimento nos lipomas orais, contudo, não estão primariamente envolvidos no crescimento tumoral dessas neoplasias." (PMID 37194849, 2023).
lung adenoma (3 papers, 2009 to 2023). A benign, well circumscribed epithelial neoplasm that arises from the bronchus or the lung parenchyma. "Recently, EGFR mutations in the kinase domain (exons 18–21) were also found in 14% of lung adenomas/adenocarcinomas from FEN1 mutant knock-in mice." (PMID 19789704, 2009). "In one animal model, development of urethane-induced lung adenomas in male A/J mice was inhibited by an EGFR-tyrosine kinase (TK) domain inhibitor, despite a lack of any mutation in the EGFR-TK domain, which was proposed to be due to activated EGFR signaling." (PMID 25364399, 2014).
lymphangioleiomyomatosis (3 papers, 2014 to 2020). A multifocal neoplasm with perivascular epithelioid cell differentiation affecting almost exclusively females of child-bearing age. "Lymphangioleiomyomatosis/TSC cells secrete, probably in a tuberin-dependent manner, high amounts of IL-6 and IL-8 that cannot be significantly affected by the exposure to rapamycin or anti-EGFR antibodies." (PMID 24606538, 2014).